ERCC6 (ERCC excision repair 6, chromatin remodeling factor)
Diseases named in the same sentence as ERCC6 in open-access papers (continued):
Sharing a sentence is not in itself a finding about the gene and the disease.
breast carcinoma (12 papers, 2014 to 2025). "Several proteins involved in this pathway are associated with breast cancer prognosis (including ERCC6 and POSTN34,35) and/or sensitivity/resistance to endocrine or other chemotherapy (including EGFR, ABL1, GNA13, and PTK736–39)." (PMID 39030258, 2024). "In comparison, our findings suggest 30% to threefold increased risk of breast cancer for ERCC6 variations with MAF of 11.8–40.9% in the general population." (PMID 33277540, 2020). "Haplotype analysis revealed borderline significant association of breast cancer with ERCC6 Hap 5 (OR 1.30, 95% CI 1.00–1.69, p = 0.048)." (PMID 33277540, 2020). "We found that the mutation frequency of ERCC6 (1.8%) in breast tumors was similar to those of known breast cancer susceptibility genes, such as BRCA1 (2.9%), BRCA2 (2.9%), BLM (1.9%), FGFR2 (1.5%), and CHEK2 (1.0%)." (PMID 33277540, 2020). "Haplotype analysis revealed statistically-significant increased risk of breast cancer with ERCC6 Hap 2 (OR 1.36, 95% CI 1.03–1.78, p = 0.03)." (PMID 33277540, 2020). "The other ERCC6 variations associated with breast cancer in our study were rs3750749, rs4253082, and rs1012553, all located in the introns, and rs2228528 and rs2229760, which are missense variants in the exons." (PMID 33277540, 2020). "Analysis of TCGA breast tumors also revealed a higher mutation frequency for all known breast cancer susceptibility genes and for ERCC6 and ERCC8 compared to the average for all other genes." (PMID 33277540, 2020). "We report on the analysis of raw multiomics data from several relevant GWAS, transcriptome, and somatic mutation datasets to test the association of breast cancer with two candidate genes, ERCC6 and ERCC8." (PMID 33277540, 2020). "One ERCC6 SNP, rs2229760 (NC_000010.11:g.49472987G > A) was associated with an increased risk for breast cancer among heterozygotes (OR 1.40, 95% CI 1.08–1.83, p = 0.010)." (PMID 33277540, 2020). "Additionally, germline variants and genetic polymorphisms in the ERCC6 gene have been associated with early onset breast cancer and an elevated risk of lung cancer, respectively." (PMID 37461096, 2023). "Integrative genomics approach suggests that ERCC6 may be a previously unreported low- to moderate-risk breast cancer susceptibility gene, which may also interact with ERCC8." (PMID 38091511, 2022). "This analysis revealed that high-penetrance breast cancer susceptibility genes had higher mutation frequencies than medium- and low-penetrance genes, which had similar mutation frequencies to each other and to ERCC6 and ERCC8." (PMID 33277540, 2020). "One ERCC6 SNP, rs3750751, was associated with a significantly increased risk (OR 1.35, 95% CI 1.01–1.80, p = 0.04) of breast cancer among heterozygotes in BPC3, and the trend (i.e., increasing number of variant alleles) was also significant (OR 1.38, 95% CI 1.05–1.81, p = 0.02)." (PMID 33277540, 2020). "Our candidate-gene association study involving individual analysis of four GWAS datasets (containing total of 2882 cases and 4397 controls) found 30% to threefold increased risk of breast cancer (OR 1.30 with rs2228528 in WHI to OR 2.91 with rs3750751 in CGEMS) conferred by six ERCC6 variations." (PMID 33277540, 2020). "Statistically significant increased risk of breast cancer in WHI was found with heterozygotes at ERCC6 rs1012553 (NC_000010.11:g.49532097A > T) (OR 1.35, 95% CI 1.07–1.71, p = 0.01) and rs2228528 (NC_000010.11:g.49524234C > T) (OR 1.29, 95% CI 1.01–1.66, p = 0.04)." (PMID 33277540, 2020). "Our candidate-gene association analyses of GWAS datasets suggested an increased risk of breast cancer with ERCC6 (main effect: 1.29 ≤ OR ≤ 2.91, 0.005 ≤ p ≤ 0.04, 11.8 ≤ MAF ≤ 40.9%), and implicated its interaction with ERCC8 (joint effect: 3.03 ≤ OR ≤ 5.31, 0.01 ≤ pinteraction ≤ 0.03)." (PMID 33277540, 2020).
breast carcinoma (continued). "Three ERCC6 SNPs, rs3750751 (NC_000010.11:g.49457882C > T), rs3750749 (NC_000010.11:g.49476182A > G), and rs4253082 (NC_000010.11:g.49509540C > T), were associated with an increased risk for breast cancer in CGEMS." (PMID 33277540, 2020). "Our integrative genomics approach suggests that ERCC6 may be a previously unreported low- to moderate-risk breast cancer susceptibility gene, which may also interact with ERCC8." (PMID 33277540, 2020). "Diplotype analysis revealed statistically-significant association of breast cancer with three diplotypes in ERCC6; these included 2/5 (OR 2.65, 95% CI 1.14–6.17, p = 0.024), 1/6 (OR 3.89, 95% CI 1.42–10.66, p = 0.008), and 4/4 (OR 2.92, 95% CI 1.04–8.22, p = 0.042)." (PMID 33277540, 2020). "We suggest that mutations in the ERCC6 gene could be considered as potential risk factors for breast cancer." (PMID 25923920, 2015). "Carrying a variant ERCC6 therefore will cause a less-efficient DNA repair response and could therefore lead to an increased predisposition to breast cancer." (PMID 25923920, 2015). "An integrative genomic analysis demonstrated that CSB expression is upregulated in breast cancer, and that there is a 30–300% increased risk of breast cancer conferred by six different ERCC6 variations, one of which is in the 3′ UTR and may affect miRNA binding." (PMID 36142121, 2022). "Reports claimed that let-7c-5p suppresses the proliferative ability of breast cancer cells via targeting ERCC6 and induces autophagy; let-7c-5p restrains cancer development by inhibiting c-Myc in liver cancer." (PMID 35368660, 2022). "Joint effect analysis revealed increased risk of breast cancer with the ERCC8 0/0 and ERCC6 2/4 diplotype combination (OR 5.31, 95% CI 1.22–23.09, p = 0.026) and the ERCC8 0/5 and ERCC6 0/0 diplotype combination (OR 5.09, 95% CI 1.23, 21.03, p = 0.025) compared with the reference category." (PMID 33277540, 2020). "Using a hypothesis-driven (candidate-gene) integrative genetic epidemiologic approach to analysis of raw multi-omics data, we tested the association of ERCC6 and ERCC8 with peri- and post-menopausal breast cancer." (PMID 33277540, 2020). "Joint effect analysis revealed increased risk of breast cancer with the ERCC8 1/1 and ERCC6 2/5 diplotype combination (OR 3.03, 95% CI 1.16–7.91, p = 0.024) and the ERCC8 1/1 and ERCC6 1/6 diplotype combination (OR 3.27, 95% CI 1.17, 9.18, p = 0.024) compared with the reference category." (PMID 33277540, 2020). "Therefore, we analyzed the segregation with breast cancer of the SNVs affecting ERCC6 (p.Ala62Thr) and WRN (p.Ala616Pro) in a family with reported breast cancer affecting three generations (case_574)." (PMID 25923920, 2015). "We found significant upregulation of ERCC6 (p = 7.95 × 10–6) and ERCC8 (p = 4.67 × 10–6) in breast cancer and similar frequencies of ERCC6 (1.8%) and ERCC8 (0.3%) mutations in breast tumors to known breast cancer susceptibility genes such as BLM (1.9%) and LSP1 (0.3%)." (PMID 33277540, 2020). "Haplotype and diplotype analysis did not reveal any statistically-significant associations in the entire BPC3 dataset; however, when stratified by cohort, significant association of ERCC6 Hap 6 (OR 1.65, 95% CI 1.02–2.68, p = 0.04) with breast cancer was detected in PBCS (results not shown)." (PMID 33277540, 2020). "In contrast, the ERCC6 p.Ala62Thr SNV segregated with breast cancer in the same family and it was not detectable in the father or control samples." (PMID 25923920, 2015). "Four known biomarkers (CHEK2 in both plasma and urine, CDKN1B, PCNA, and THBS1) were identified as false positives (red) in our breast cancer list, and seven (KRAS, GDNF in both breastmilk and plasma, MYCL1 in both blood and serum, CD40LG, CGA, CTAG1A, ERCC6, and HRAS) in our lung cancer list." (PMID 25379168, 2014).
lung carcinoma (10 papers, 2012 to 2025). "While excision repair cross-complementing group 6 (ERCC6) has been linked to lung cancer risk, its specific roles in LUAD progression are poorly understood." (PMID 40691138, 2025). "One case-control analysis revealed ERCC6 rs3793784:C>G alters its transcriptional activity and may confer personalized susceptibility to lung cancer." (PMID 23118991, 2012).
gastric cancer (8 papers, 2014 to 2025). A primary or metastatic malignant neoplasm involving the stomach. "ERCC6 rs1917799 also showed a significant interaction with ERCC8 rs158916 to reduce gastric cancer risk." (PMID 28562347, 2017). "The pair of pri-let-7a-1 rs10739971 polymorphism and ERCC6 rs1917799 polymorphism had an OR of their interaction of 2.59 for gastric cancer risk, which was greater than their individual single-locus effects of 0.92 and 1.07, respectively." (PMID 24586594, 2014). "We found that miRNA polymorphism and PGC and ERCC6 polymorphisms showed strong statistical association with gastric cancer or atrophic gastritis." (PMID 24586594, 2014). "The results indicated that pri-let-7a-1 rs10739971 polymorphism and ERCC6 rs1917799 polymorphism had interaction effects for gastric cancer risk (Pinteraction = 0.026)." (PMID 24586594, 2014). "ERCC6 rs1917799 T>G polymorphism in the promoter region was associated with increased gastric cancer risk in a Chinese population." (PMID 24586594, 2014). "The interaction of pri-let-7a-1 rs10739971 and ERCC6 rs1917799 polymorphisms in the risk of gastric cancer/atrophic gastritisa." (PMID 24586594, 2014). "However, recent reports show that ERCC6 leads to increased predisposition to breast and gastric cancers." (PMID 35912179, 2022). "The aim of this study was to investigate the interaction effects of pri-let-7a-1 rs10739971 with pepsinogen C (PGC) and excision repair cross complementing group 6 (ERCC6) gene polymorphisms and its association with the risks of gastric cancer and atrophic gastritis." (PMID 24586594, 2014). "Thus, we analyzed the interaction effect of pri-let-7a-1 rs10739971 polymorphism and PGC and ERCC6 polymorphisms, and its associations, with the risks of gastric cancer and atrophic gastritis." (PMID 24586594, 2014). "High ERCC6 expression was observed in gastric cancers of Borrmman class I–II, TNM stage I–II, intestinal-type and without perineural invasion." (PMID 34316408, 2021). "This study aimed to evaluate the interactions between single nucleotide polymorphisms of ERCC6 (rs1917799) and ERCC8 (rs158572 and rs158916) in gastric cancer and its precancerous diseases." (PMID 28562347, 2017). "Population-based epidemiologic studies have shown that ERCC6 and ERCC8 polymorphisms have a significant impact on the risk of some human malignancies, including gastric cancer." (PMID 28562347, 2017). "In conclusion, ERCC6 rs1917799, ERCC8 rs158572 and rs158916 demonstrated pairwise epistatic interactions to associate with chronic atrophic gastritis and gastric cancer risk." (PMID 28562347, 2017). "More interestingly, several association studies also found that SNPs located in DNA repair related genes including ERCC4, ERCC6, Ku70m, APE1, XRCC1, and XPD exhibited a differential effect between genders on gastric cancer susceptibility." (PMID 26402912, 2015). "Sequenom MassARRAY platform method was used to detect polymorphisms of pri-let-7a-1 rs10739971 G→A, PGC rs4711690 C→G, PGC rs6458238 G→A, PGC rs9471643 G→C, and ERCC6 rs1917799 in 471 gastric cancer patients, 645 atrophic gastritis patients and 717 controls." (PMID 24586594, 2014). "For instance, ERCC5 rs1047768 variant reduced the risk of gastric cancer, ERCC3 rs4150403 was associated with an increased susceptibility to head and neck cancer in Caucasians, and ERCC6 rs4253132 polymorphism decreased the risk of head and neck cancer among African Americans." (PMID 33557438, 2021). "Pearson’s correlation analysis using data from 37 gastric cancer cell lines showed that ERCC6 mRNA expression was significantly correlated with JAK2 protein expression (r = −0.345; P = 0.037), and ERCC8 mRNA expression was associated with Src protein expression (r = −0.417; P = 0.010)." (PMID 34316408, 2021).
gastric cancer (continued). "Our results demonstrated pairwise epistatic interactions between ERCC6 and ERCC8 SNPs that ERCC6 rs1917799-ERCC8 rs158572 combination was associated with decreased risk of chronic atrophic gastritis and increased risk of gastric cancer." (PMID 28562347, 2017). "On the basis of the findings in the present study, it is reasonable to suggest that let-7a may participate in the processes of PGC inducing atrophic gastritis and ERCC6 inducing gastric cancer." (PMID 24586594, 2014). "ERCC2 rs50871 G/T, ERCC6 rs1917799 G/T and DDB2 rs3781619 A/G polymorphisms were significantly associated with shorter OS, while ERCC1 rs3212961 A/C, ERCC5 rs2094258 A/G and DDB2 rs830083 C/G could predict favorable OS of gastric cancer patients." (PMID 35955506, 2022). "Through analyzing the expression data of 37 gastric cancer cell lines from CCLE, we figured out that ERCC6 mRNA expression was correlated with JAK2 protein expression, and that ERCC8 mRNA expression was related to Src protein expression." (PMID 34316408, 2021). "In our previous study, we systematically analyzed the association of 43 SNPs of ten key NER pathway genes including ERCC6, ERCC8 with survival of gastric cancer (GC) patients, and found that ERCC6 SNP could predict GC prognosis." (PMID 28562347, 2017). "In situ ERCC6 and ERCC8 protein expression were detected by immunohistochemistry in 109 chronic superficial gastritis, 109 chronic atrophic gastritis and 109 gastric cancer cases." (PMID 28562347, 2017). "Correlation between ERCC6/ERCC8 expression and survival in gastric cancer." (PMID 34316408, 2021). "The expressions of ERCC6, ERCC8 and ERCC6-ERCC8 combination have similarities that higher positivity was observed in chronic superficial gastritis compared with chronic atrophic gastritis and gastric cancer." (PMID 28562347, 2017). "However, the relationship between individual and joint expressions of ERCC6/ERCC8 and clinicopathological parameters as well as prognosis of gastric cancer (GC) still remains unclear." (PMID 34316408, 2021).
bladder cancer (6 papers, 2008 to 2025). "The frequencies of OGG1 Ser326Cys (rs1052133), XRCC1 Arg399Gln (rs25487), XPD Asp312Asn (rs1799793), and ERCC6 Met1097Val (rs2228526) polymorphisms have been recently determined in the bladder cancer (BC) patients as compared with clinically healthy residents of Belarus." (PMID 26649138, 2016). "Our study revealed a favorable correlation between the expression of ERCC2 and ERCC6 in patients with bladder cancer (BLCA) and the BLCA stem cell index." (PMID 39192988, 2024). "Garcia-Closas evaluated the influence of common genetic variation in the NER pathway on bladder cancer risk by analyzing 22 single nucleotide polymorphisms (SNP) in seven NER genes (XPC, RAD23B, ERCC1, ERCC2, ERCC4, ERCC5, and ERCC6)." (PMID 19055767, 2008).
xeroderma pigmentosum (5 papers, 2008 to 2024). Xeroderma pigmentosum (XP) is a rare genodermatosis characterized by extreme sensitivity to ultraviolet (UV)-induced changes in the skin and eyes, and multiple skin cancers. "g.,ERCC2/XPD,ERCC3/XPB,ERCC4/XPF,ERCC5/XPG,ERCC6/CSB, andERCC8) in the NER pathway frequently cause Xeroderma pigmentosum, trichothiodystrophy, or Cockayne syndrome." (PMID 35593466, 2022). "Apart from the two principal complementation groups of CS (CSA and CSB) with mutations in the ERCC8 and ERCC6 genes, respectively, a small number of CS cases have been reported to carry mutations in the ERCC1 and ERCC4 (xeroderma pigmentosum complementation group F-XPF) genes." (PMID 33920220, 2021).
age-related macular degeneration (4 papers, 2010 to 2022). Age-related loss of vision in the central portion of the retina (macula), secondary to retinal degeneration. "Previously, ERCC6 upregulation was linked with aging-related diseases (age-related macular degeneration, etc.)." (PMID 35392536, 2022). "Defects in ERCC6 cause CS and age-related macular degeneration." (PMID 31921313, 2019).
Cockayne syndrome type B (4 papers, 2020 to 2025). "Mutations in ERCC6 cause Cockayne syndrome type II, a disorder characterized by neurodevelopmental deficits and premature aging." (PMID 41350539, 2025). "Together with a hemizygous variant in the ERCC6 gene, the diagnosis of Cockayne syndrome type B was established." (PMID 40428344, 2025).
colorectal cancer (4 papers, 2018 to 2022). A primary or metastatic malignant neoplasm that affects the colon or rectum. "Among genes with downregulated methylation in HL60/MX2, ERCC6 was directly involved in regulating the response to 5-FU chemotherapy in colorectal cancer." (PMID 35865472, 2022). "A previous lab study showed that knockdown of ERCC6 could sensitize HCT116 cells to 5-Fluorouracil in xenograft mouse models and colorectal cancer patients with high ERCC6 expression exhibited shorter overall survival (Zhao, Zhang & Li, 2017)." (PMID 34316408, 2021). "There were no human data on chemotherapy agents related to ERCC6 other than platinum chemotherapy agents, and there was one report showing that the anticancer effect of 5-fluorouracil was significantly increased when ERCC6 was knocked down in colorectal cancer cell lines and xenograft models." (PMID 33801891, 2021).
UV-sensitive syndrome (4 papers, 2017 to 2025). UV-sensitive syndrome is a condition that is characterized by sensitivity to the ultraviolet (UV) rays in sunlight. "Homozygous ERCC6/ERCC8 mutations also result in UV-sensitive syndrome." (PMID 29057985, 2017). "Indeed, variants in ERCC6 and ERCC8 genes have been also associated with the UV sensitive syndrome (UVSS), a milder form clinically characterized by mild cutaneous symptoms." (PMID 35248096, 2022).
skin cancer (3 papers, 2017 to 2021). "Finally, a study, in which 193 DNA repair genes were evaluated in regard to their mutation frequency in sequenced tumor samples from the COSMIC database, revealed that ERCC6 is among the top 20 most frequently mutated genes in lung, breast and skin cancers." (PMID 33920220, 2021). "Recently, it was reported that ERCC6 and ERCC8 deficient mice were more susceptible to both UV- and chemically-induced skin cancer." (PMID 28562347, 2017). "For instance, in contrast to human CS patients, who do not develop skin cancer, ERCC6 mutant mice show increased susceptibility to skin cancer." (PMID 31037510, 2020).
atrophic gastritis (2 papers, 2014 to 2017). "We also performed protein level analysis to compare ERCC6 and ERCC8 expression (alone or in combination) in chronic superficial gastritis (CSG), chronic atrophic gastritis (CAG) and GC, and to correlate SNPs jointly with gene expression." (PMID 28562347, 2017).
Cockayne syndrome A (2 papers, 2020 to 2022). "This event calls into action numerous factors, including the TFIIH complex, XPA, RPA, and the TC-NER proteins, Cockayne syndrome A (CSA, a.k.a., ERCC8), and CSB (a.k.a., ERCC6)." (PMID 35456958, 2022). "RNA polymerase II stalls at the site of DNA damage, resulting in the recruitment of cockayne syndrome type A and type B proteins (CSA and CSB) (ERCC8 and ERCC6)." (PMID 35582447, 2020).